KRTAP13-2 (keratin associated protein 13-2)
Description:
In the hair cortex, hair keratin intermediate filaments are embedded in an interfilamentous matrix, consisting of hair keratin-associated proteins (KRTAP), which are essential for the formation of a rigid and resistant hair shaft through their extensive disulfide bond cross-linking with abundant cysteine residues of hair keratins. The matrix proteins include the high-sulfur and high-glycine-tyrosine keratins (By similarity).
Synonyms: KAP13-2
Tractability: No criterion of Open Targets' tractability assessment is met for any kind of drug.
Gene: Protein-coding gene on chromosome 21 (30,371,390 to 30,372,271, reverse strand). Ensembl gene ENSG00000182816.
Pathways (Reactome):
Developmental Biology: Keratinization
Gene Ontology:
Molecular function: protein binding; structural molecule activity
Cellular component: cytosol; keratin filament
Genetic constraint (gnomAD): Missense variants: 177 observed, 167.84 expected, observed/expected ratio (o/e) 1.05, 90% interval 0.93 to 1.2. Synonymous variants: 70 observed, 68.19 expected, observed/expected ratio (o/e) 1.03, 90% interval 0.85 to 1.25.
Homologues: Orthologues: chimpanzee KRTAP13-2 (98% identical), rat Krtap13-1 (63% identical), rabbit KRTAP13-4 (61% identical), mouse Krtap13-1 (61% identical). Paralogues in human: KRTAP13-1 (89% identical), KRTAP13-4 (68% identical), KRTAP13-3 (64% identical), KRTAP15-1 (47% identical), KRTAP11-1 (35% identical), KRTAP26-1 (26% identical), KRTAP27-1 (25% identical), KRTAP25-1 (19% identical).
Diseases named in the same sentence as KRTAP13-2 in open-access papers:
KRTAP13-2 is named in the same sentence as 4 diseases in open-access papers, as found by Europe PMC text mining. Sharing a sentence is not in itself a finding about the gene and the disease. The quoted sentences say what the papers report.
melanoma (1 paper, 2022). A malignant, usually aggressive tumor composed of atypical, neoplastic melanocytes. "Genes, such as members of the keratin family (KRT17, KRTDAP, KRT6B, KRT14, KRTAP13-2) are expressed more in primary tumor, possibly indicating the differentiated status of less advanced cancers, or this could be a disruption in their normal expression by melanoma processes." (PMID 36553569, 2022).
rectal cancer (1 paper, 2022). A primary or metastatic malignant neoplasm that affects the rectum. "KRTAP13-2 encodes Keratin Associated Protein 13-2, which was also downregulated in rectal cancer." (PMID 36293321, 2022).
KRTAP13-2 also shares sentences with these, for which no sentence is quoted: cancer (1 paper); tumor (1).